MIR6514 (microRNA 6514)
Synonyms: hsa-mir-6514; mir-6514
Gene: MicroRNA gene on chromosome 11 (62,792,702 to 62,792,771, reverse strand). Ensembl gene ENSG00000274066.
Homologues: Orthologues: chimpanzee MIR6514 (100% identical).